MNX1 (motor neuron and pancreas homeobox 1)
Diseases named in the same sentence as MNX1 in open-access papers (continued):
Sharing a sentence is not in itself a finding about the gene and the disease.
breast carcinoma (6 papers, 2018 to 2025). "The regulatory association between MNX1 and the expression of breast cancer receptors remains uncharted." (PMID 38339428, 2024). "In agreement with results from human cancer cells, the depletion of MNX1 via CRISPR/Cas9 also reduced PD‐L1 expression in 4T1 mouse breast cancer cells and mEC25 mouse ESCC cells." (PMID 39912421, 2025). "MNX1 also promotes the malignant progression of cervical cancer, breast cancer, and colorectal cancer." (PMID 38339428, 2024). "In summary, our study reveals that MNX1 enhances the sensitivity of HER2-positive breast cancer cells to anti-HER2 therapeutics." (PMID 38203393, 2023). "This study explored the mechanisms underlying the effect of the motor neuron and pancreatic homeobox 1 (MNX1) genes on drug sensitivity in HER2-positive breast cancer." (PMID 38203393, 2023). "Our study found that MNX1 can increase the sensitivity of HER2-positive breast cancer cells to lapatinib and pyrotinib, thereby further improving the functional phenotype of MNX1 in breast cancer." (PMID 38203393, 2023). "Analysis of the TCGA database showed that MNX1 was relatively highly expressed in HER2-positive breast cancer compared with other types of breast cancer." (PMID 38203393, 2023). "In the half-maximal drug inhibitory concentration (IC50) experiment, we found that MNX1 overexpression promoted the sensitivity of HER2-positive breast cancer cells to TKI drugs." (PMID 38203393, 2023). "In the multivariate analysis, we included variables with a p value < 0.05 and found that axillary lymph node metastasis (p < 0.0001) and MNX1 expression level (p = 0.031) were independent prognostic factors that affected HER2-positive breast cancer DFS." (PMID 38203393, 2023). "In summary, this study is the first to show that MNX1 enhances sensitivity to anti-HER2-targeted therapy in HER2-positive breast cancer by transcriptional activation of M6PR." (PMID 38203393, 2023). "We further plotted the survival curves of overall and disease-free survival (DFS) in patients with HER2-positive breast cancer with high or low MNX1 expression." (PMID 38203393, 2023). "In vitro functional tests showed that upregulation of MNX1 significantly increased the sensitivity of HER2-positive breast cancer cells to lapatinib and pyrotinib." (PMID 38203393, 2023). "We found that MNX1 was highly expressed in HER2-positive breast cancer compared with other types of breast cancer." (PMID 38203393, 2023). "Targeting macrophages or MNX1 may provide new avenues for endocrine therapy and targeted treatment of breast cancer patients with lymph node metastasis." (PMID 38339428, 2024). "In conclusion, MNX1 may serve as a prognostic marker for patients with HER2-positive breast cancer, and its expression may facilitate clinical screening of patients sensitive to anti-HER2-targeted therapy." (PMID 38203393, 2023). "MNX1 was highly expressed in the pCR group in both the public database and data obtained from our center, suggesting that MNX1 may be used to predict the sensitivity of neoadjuvant chemotherapy in patients with HER2-positive breast cancer." (PMID 38203393, 2023). "have reported that the percentage of nuclei expressing of MNX1 is increased in breast carcinoma." (PMID 30368216, 2018). "To explore the relationship between the MNX1 protein level and clinical prognosis of patients with HER2-positive breast cancer, we used tissue microarray data of 183 patients from our center to perform immunohistochemical staining and scored the patients by the staining intensity of MNX1." (PMID 38203393, 2023). "As expected, Cell Counting Kit‐8 (CCK‐8) assays showed that the depletion of MNX1 suppressed the growth of human and mouse ESCC cells as well as human and mouse breast cancer cells in vitro." (PMID 39912421, 2025).
breast carcinoma (continued). "As potential transcription factors regulating the expression of ERBB2, MNX1 and NKX2-2 emerged as the highest-expressed in HER2-E breast cancer, followed by Luminal B breast cancer." (PMID 38339428, 2024). "By detecting the expression of MNX1 in HER2-positive breast cancer cells, stably transfected MNX1 overexpression and knockdown cells were constructed from BT474 and JIMT-1 breast cancer cells." (PMID 38203393, 2023). "Likewise, the depletion of MNX1 mediated by short hairpin RNA (shRNA) also led to a decrease in PD‐L1 mRNA and protein levels in MCF7 breast cancer cells." (PMID 39912421, 2025). "For breast cancer, bioinformatics analyses of MNX1 have been carried out in previous research and showed that its expression in HER2-positive breast cancer is significantly higher than that in other types of breast cancer." (PMID 38203393, 2023). "To select appropriate cell lines for the construction of stably transfected overexpression and knockdown cells, we detected MNX1 RNA and protein expression levels in normal breast epithelial HBL100 cells and the breast cancer cell lines MDA-MB-231, T47D, BT474, SK-BR-3, HCC1954, and JIMT-1." (PMID 38203393, 2023). "Therefore, in the future, it would be beneficial to evaluate MNX1 expression to screen for populations sensitive to clinical anti-HER2-targeted therapy and promote precise treatments for breast cancer." (PMID 38203393, 2023). "MNX1 was significantly upregulated in the pCR group compared with the non-pCR group in both sequencing datasets, suggesting that MNX1 might be correlated with drug sensitivity in HER2-positive breast cancer." (PMID 38203393, 2023). "Moreover, current studies have not focused on MNX1 drug sensitivity in HER2-positive breast cancer." (PMID 38203393, 2023).
colorectal cancer (5 papers, 2019 to 2025). A primary or metastatic malignant neoplasm that affects the colon or rectum. "Here, overexpressed MNX1 promoted proliferation, invasion, and migration of colorectal cancer cells, and downregulated levels yielded the opposite result." (PMID 37779874, 2023). "Additionally, we analyzed the GEPIA and StarBase databases and discovered significant MNX1 upregulation in colorectal cancer." (PMID 37779874, 2023). "In conclusion, we proposed that E2F4 may act as a transcriptional regulator, activating MNX1 to induce colorectal cancer development." (PMID 37779874, 2023). "Interestingly, the analyses showed that MNX1 was closely associated with immune‐related functions and pathways in multiple types of human cancers, including ESCA, breast invasive carcinoma (BRCA), colorectal cancer (CRC), and lung adenocarcinoma (LUAD)." (PMID 39912421, 2025). "Summarily MNX1 could influence the migratory and invasive capacity of colorectal cancer cells." (PMID 37779874, 2023). "Western blotting, q-PCR and immunohistochemistry et, al. were used to detect the level of MNX1 in patients with colorectal cancer, and Chip-PCR was used to detect the targeted binding ability of E2F4 and MNX1." (PMID 37779874, 2023).
diabetes (5 papers, 2015 to 2024). "Likewise, Hnf1b, Gata4/Gata6, Pdx1 or Mnx1-deficient mice fail to develop pancreas of normal size and rather develop diabetes." (PMID 39322760, 2024). "In addition to NKX6–1 we found variants in WFS1, RFX6 and 7 other genes associated with monogenic forms of diabetes (AKT2, EIF2AK3, GLIS3, HADH, MNX1, NKX2–2, and PTF1A) and they may be relevant to development of MODY." (PMID 29439679, 2018). "Furthermore, several genes involved in the endocrine specification and diabetes development were significantly downregulated, such as HES1, INSM1, HNF1A, NEUROD1, NGN3, NKX2.2, GIPR, MNX1, PROX1, TCF7L2, and HHEX." (PMID 33473118, 2021).
glioma (4 papers, 2022 to 2024). A benign or malignant brain and spinal cord tumor that arises from glial cells (astrocytes, oligodendrocytes, ependymal cells). "In terms of the tumor microenvironment, MNX1 was found to be ectopically expressed in glioma cells and associated with glioma grade." (PMID 39184045, 2024). "Expression of the transcription factor motor neuron and pancreatic homeobox 1 (MNX1) correlates with the degree of malignancy of glioma cells." (PMID 39062119, 2024). "Therefore, MNX1 is considered a potential target for glioma therapy to achieve anoikis induction." (PMID 39062119, 2024).
insulinoma (4 papers, 2018 to 2024). "It was also recently determined that MNX1 plays a significant role in cell proliferation in human insulinomas." (PMID 30012177, 2018). "Moreover, MNX1 has been testified to expedite insulinoma cell proliferation via interaction with NONO protein." (PMID 32850524, 2020).
MODY (4 papers, 2018 to 2024). "MNX1 was reported as a rare gene potentially associated with MODY also in a Southern Indian population." (PMID 39201476, 2024). "Like GCK and RFX6, homozygous variants of MNX1 could contribute to neonatal diabetes development, while heterozygous ones to rare cases of MODY." (PMID 39201476, 2024). "Next 357 selected patients, in whom no damaging variants were found in 12 major genes causing MODY, were screened for the presence of pathogenic variants in four candidate genes (MNX1, RFX6, NKX2.2, and NKX6.1)." (PMID 34019234, 2021). "Interestingly, 3 genes involved in MODY signaling pathway, including Bhlha15, Mnx1 and Nkx6.1, changed." (PMID 29879176, 2018). "In the MNX1 gene, no variant was identified that could potentially cause MODY in the studied population." (PMID 34019234, 2021). "Although the variants in NKX2–2, RFX6 and MNX1 have been found in recessively inherited neonatal diabetes, variants in NKX6–1 have not thus far been found in neonatal diabetes or MODY." (PMID 29439679, 2018).
prostate carcinoma (4 papers, 2018 to 2024). A carcinoma that arises from epithelial cells of the prostate gland. "MNX1 is a homeobox gene known as an oncogene in infant AML and prostate cancer." (PMID 38339428, 2024).
cervical cancer (3 papers, 2020 to 2024). A primary or metastatic malignant neoplasm involving the cervix. "Our results suggested that MNX1 was a potential diagnostic marker and therapeutic target for cervical cancer patients." (PMID 32850410, 2020). "All this results indicated that MNX1 played a critical role in cancer growth and cell cycle progression, and MNX1 might serve as a useful diagnostic and treatment target for cervical cancer." (PMID 32850410, 2020). "The overexpression of MNX1 correlated with advanced clinical stages and poorer prognosis of cervical cancer patients." (PMID 32850410, 2020). "In this study, we proved that MNX1 exerted an oncogenic role in cervical cancer via suppressing the expression of p21 with binding to its promoter region." (PMID 32850410, 2020). "In this study, we identified MNX1, a transcription factor of homeobox family, was significantly upregulated and involved in the progression of cervical cancer." (PMID 32850410, 2020). "In summary, our study revealed that MNX1 exerted an oncogenic role in cervical cancer via repressing the transcription of p21cip1 and thus accelerating cell cycle progression." (PMID 32850410, 2020). "In terms of mechanism, we found that MNX1 promoted tumor growth of cervical cancer via accelerating the progression of the cell cycle, especially by modulating the expression of p21cip1." (PMID 32850410, 2020). "The high expression level of MNX1 correlated with poorer clinicopathologic characteristics in cervical cancer patients." (PMID 32850410, 2020). "The upregulated MNX1 correlated with more advanced clinical pathological characteristics and poorer prognosis of cervical cancer patients." (PMID 32850410, 2020). "The knockdown or overexpressed MNX1 inhibited or promoted aggressiveness of cervical cancer, including proliferation, migration, and invasion capacities, by enhancing or repressing the transcription of p21cip1 thus regulating the G2/M cell cycle transition." (PMID 32850410, 2020). "QRT-PCR, western blot, and IHC showed that MNX1 was abnormally overexpressed in cervical cancer tissues and cell lines." (PMID 32850410, 2020). "Our results revealed that MNX1 was significantly upregulated in cervical cancer and correlated with poorer prognosis." (PMID 32850410, 2020). "The MNX1-p21cip1-pThr161CDK1 axis played crucial roles in the progression of cervical cancer and meanwhile provided new evidence for the pathogenesis of cervical cancer." (PMID 32850410, 2020). "And in this study, three cervical cancer cells (HeLA, Siha, and C33A) were used to study the function of MNX1." (PMID 32850410, 2020). "The expression of MNX1 in cervical cancer tissues were significantly higher than adjacent tissues in 85% (34/40) of 40 cervical cancer patients (p < 0.001)." (PMID 32850410, 2020). "Analysis of TCGA dataset revealed that the mRNA expression of MNX1 was remarkably upregulated in cervical cancer tissues compared with para-tumor tissues (p = 0.0003)." (PMID 32850410, 2020). "The RTCA proliferation assay, EDU assay, and colony formation assay showed that knockdown of MNX1 inhibited the proliferation ability of cervical cancer in HeLa and Siha cells." (PMID 32850410, 2020). "Consistently, our results showed that ectopic expression of MNX1 promotes proliferation, migration, and invasion of cervical cancer cells." (PMID 32850410, 2020). "IHC assays based on tissue microarrays (TMAs) were performed to detect the protein expression of MNX1 in 62 paired human cervical cancer tissues and para-tumor tissues, and results showed that staining scores of MNX1 were higher in cancer tissues (p < 0.0001)." (PMID 32850410, 2020). "And in our study, MNX1 was also confirmed to be upregulated in cervical cancer and enhance the progression of cervical cancer." (PMID 32850410, 2020). "In summary, we identified the homeobox member MNX1 as a tumor-promoting gene in cervical cancer." (PMID 32850410, 2020).
cervical cancer (continued). "We believe that there are other genes beside p21 regulated by MNX1 in cervical cancer." (PMID 32850410, 2020). "The aim of this study is to identify the expression and function of MNX1 in cervical cancer." (PMID 32850410, 2020). "And as the downregulation of MNX1 inhibited tumor growth of cervical cancer, MNX1 may represent promising targets for the diagnosis and anti-tumor therapy in cervical cancer patients." (PMID 32850410, 2020). "Moreover, RTCA migration assay, transwell assay, and matrigel assay, and wound healing assay revealed that silencing MNX1 inhibited the ability of cervical cancer cells to migrate and invade." (PMID 32850410, 2020).
hepatocellular carcinoma (3 papers, 2018 to 2022). A malignant tumor that arises from hepatocytes. "The finding of increased MNX1 levels in patients with acute leukemia and colorectal or hepatocellular cancers suggests that MNX1 protein harbors an additional tumor suppressor function." (PMID 33836786, 2021). "The past decade saw a plethora of studies highlighting the dysregulation of MNX1 in various cancers, including leukaemia, lymphoma, cancers of the breast, prostate, bladder, colorectal, brain, hepatocellular carcinomas, and pancreatic tumours." (PMID 36429006, 2022).
breast invasive carcinoma (2 papers, 2022 to 2025). "We identify early processes and potential biomarkers, including CAMK2N1, MNX1, ADCY5, HOXC11 and ANKRD22, whose reduced expression is associated with the progression of DCIS to invasive breast cancer." (PMID 35697697, 2022).
chordoma (2 papers, 2014 to 2023). Chordomas are rare malignant tumors arising from embryonic remnants of the notochord in axial skeleton. "Genes marked on the volcano plot were either implicated earlier in chordoma biology (e.g. keratins—KRT8, KRT18, KRT19, TBXT, LMX1A, and EGFR) or identified by outstanding p-value (e.g. IL11, CD24), high absolute fold-change (e.g. GABRA1) or DMR result (e.g. MNX1)." (PMID 37434245, 2023). "Chordoma-specific DMRs were also found in location of homeobox domain genes (e.g. DMRs in HOXA4, HOXA5, HOXD3, HOXD4 MNX1, and NFIX) especially on chromosome 2 at HOXD cluster." (PMID 37434245, 2023).
gastric cancer (2 papers, 2020 to 2022). A primary or metastatic malignant neoplasm involving the stomach. "Interestingly, in stomach cancer, a lower expression of MNX1 associated with inferior clinical outcomes for both OS and PFI." (PMID 36429006, 2022). "And MNX-AS1, the antisense lncRNA of MNX1, was also reported to promote the invasion and metastasis of gastric cancer through repression of CDKN1A." (PMID 32850410, 2020).
glioblastoma (2 papers, 2022 to 2026). The most malignant astrocytic tumor (WHO grade IV). "MNX1 was found to play an important role in developing anoikis resistance in glioblastoma." (PMID 41596231, 2026). "In addition to glioblastoma, MNX1 was identified as an anoikis resistance gene in many tumors such as renal cell carcinoma, colon cancer, and acute myeloid leukemia." (PMID 41596231, 2026).
Hodgkins lymphoma (2 papers, 2018 to 2020). A heterogeneous group of malignant lymphoid neoplasms of B-cell origin characterized histologically by the presence of Hodgkin and Reed-Sternberg (HRS) cells in the vast majority of cases. "Further, MNX1 was found to activate IL-6 expression in Hodgkin lymphoma cells through regulating PI3K signaling, which might participate in mediating inflammatory response." (PMID 32850524, 2020).
liver cancer (2 papers, 2019 to 2022). An epithelial or non-epithelial malignant neoplasm that arises from the liver. "Nevertheless, MNX1 and its antisenses showed statistically significant associations in grading, lymph node invasion, and staging in liver cancer." (PMID 36429006, 2022).
neonatal diabetes mellitus (2 papers, 2024). Neonatal diabetes mellitus presents as hyperglycemia, failure to thrive and, in some cases, dehydration and ketoacidosis which may be severe with coma, in a child within the first months of life. "Mutations in GATA6 are associated with human pancreas agenesis, and mutations in GATA4, and MNX1 cause permanent neonatal diabetes mellitus." (PMID 39322760, 2024). "Several homozygous variants in the MNX1 gene have already been described in the literature as associated with the phenotype of persistent neonatal diabetes mellitus (PNDM)." (PMID 38932873, 2024).
pancreatic cancer (2 papers, 2021 to 2023). "For instance, SIX1 is upregulated in the cervical 21 and pancreatic cancers 22; MNX1 correlates with multiple tumours 23-25." (PMID 37779874, 2023).
childhood leukemia (1 paper, 2023). An acute or chronic leukemia that occurs during childhood. "However, it has also been reported that MNX1 plays a dual role in childhood leukemia." (PMID 38203393, 2023).
head and neck squamous cell carcinoma (1 paper, 2020). A squamous cell carcinoma that arises from any of the following anatomic sites: lip and oral cavity, nasal cavity, paranasal sinuses, pharynx, larynx, and salivary glands. "In GSE3292 (GDS1667), HPV positive or negative head and neck squamous cell carcinoma (HNSCC) showed no expression differences of MNX1." (PMID 32850410, 2020).
Intellectual disability (1 paper, 2018). "Instead, CS phenotypes characterized by growth delay and/or facial dimorphism and/or intellectual disability are often due to deletions of long arm of chromosome 7 containing MNX1." (PMID 29801510, 2018).
lung agenesis (1 paper, 2021). "However, additional studies need to be performed to support the hypothesis of MNX1 activation by MACS1 in lung tissue as the cause of lung agenesis in our patients." (PMID 34436670, 2021).
lung carcinoma (1 paper, 2022). "In lung cancers LUAD and LUSC, only a high MNX1 expression was correlated with inferior DFI and PFI." (PMID 36429006, 2022).